INS (insulin)
Diseases named in the same sentence as INS in open-access papers (continued):
Sharing a sentence is not in itself a finding about the gene and the disease.
diabetes (continued). "Patients on insulin may represent a later disease stage, with longer-standing diabetes, but also possibly better-recognized and managed cardiovascular risk." (PMID 41153651, 2025). "The strong antioxidant capacity of MPEO from Ouazzane may support beta cell protection, enhance insulin sensitivity, and help manage oxidative complications in diabetes." (PMID 40658325, 2025). "This study proposes a Fully Recurrent Neural Network (FRNN) identification framework enhanced by a Fractional-Order (FO) learning algorithm (FRNN-FO) for modeling and identifying the chaotic behavior of insulin-glucose regulatory systems under various diabetes-related disorders." (PMID 41345203, 2025). "In addition, the lack of healthcare resources often leads to dietitian-only appointments, with limited support from a diabetes specialist who will provide a detailed plan on insulin adjustments and sick day rules." (PMID 40573112, 2025). "Vinegar could ameliorate the insulin response to food glycemic index in patients with diabetes and could decrease HbA1c with this mechanism." (PMID 39949546, 2025). "All of them went on diabetes medication insulin with dosage increasing over time." (PMID 40851781, 2025). "Administration of genetically modified strains of Lactobacillus lactis that secrete pro-insulin autoantigen and the immunomodulatory cytokine IL-10 could revert diabetes in NOD mice and increase the frequencies of local T regulatory cells." (PMID 40422866, 2025). "Evaluating IR solely by fasting insulin measurement may underestimate the true degree of IR in patients with diabetes and concomitant fatty liver." (PMID 40950956, 2025). "The development of diabetes and the need for pharmaceutical intervention to avoid late complications are significantly influenced by the insensitivity of essential metabolic organs to insulin action, including the liver, skeletal muscle, and adipose tissue." (PMID 39906612, 2025). "In addition, the m6A dot blot assay showed that the level of m6A modification decreased in people with diabetes after intensive insulin therapy (p < 0.05)." (PMID 40299682, 2025). "However, the number of patients with oral combination therapy and oral drugs combined with insulin therapy was growing, which meant that the number and mode of medication for diabetes patients in China had increased." (PMID 40260392, 2025). "One patient with type 2 diabetes mellitus was managed with both metformin and insulin treatment." (PMID 41019329, 2025). "The direct effects of OCN on energy metabolism by promoting insulin secretion, improving insulin resistance, and predicting diabetes and its complications have been widely reported in basic research and both cross-sectional and longitudinal clinical studies, and have been comprehensively reviewed." (PMID 41356002, 2025). "Earlier initiation of insulin in the group with low SES may reflect suboptimal diabetes management in this population, necessitating earlier medication intensification." (PMID 40897507, 2025). "Over the past few decades, insulin has contributed immensely to the treatment of diabetes mellitus." (PMID 41155876, 2025). "As a result, this may negatively impact on adherence to insulin therapy among patients with diabetes in Ghana in practice, which may be exacerbated if patients are not active members of NHIS." (PMID 39854487, 2025). "Three patients experienced an episode of ketoacidosis (DKA) due to insulin delivery set occlusion." (PMID 40642512, 2025). "Applications of AI in diabetes care range from early diagnosis to automated insulin dosing management and the identification of critical glycemic patterns, thereby contributing to the emergence of a new paradigm in precision medicine for diabetes." (PMID 40870448, 2025). "Notably, the observed preservation of body weight and reduction in insulin levels in LH-treated groups points to potential effects on energy partitioning, contrasting the characteristic catabolic state of diabetes." (PMID 40941061, 2025).
diabetes (continued). "Type 2 diabetes mellitus (T2DM) is a chronic metabolic disease primarily caused by a combination of two main factors: defective insulin secretion by pancreatic β-cells and the inability of insulin-sensitive tissues to respond to insulin." (PMID 41426839, 2025). "In diabetes, decreased insulin sensitivity, low HDL-C, and hypertriglyceridemia result in highly impacted blood levels of cholesteryl ester transfer protein (CETP), which facilitates the transport of cholesterol ester and triacylglycerol between HDL-C and LDL-C particles." (PMID 40314056, 2025). "For instance, the ancillary study of the Diabetes Control and Complications Trial (DCCT) revealed that intensive insulin therapy in T1D was associated with profound weight gain, increasing body mass index (BMI), especially in the top quartile, blood pressure, and adverse lipid profiles." (PMID 41199877, 2025). "The basic principle of the stem cell-based approach in diabetes therapy following cadaveric islet transplantation using Edmonton protocol is to differentiate hPSCs into insulin-expressing β-cells and transplant them to diabetic patients which helps to circumvent healthy islet donor shortage." (PMID 39883142, 2025). "Consensus regarding optimal peri-operative diabetes management is growing, with case reports and series reporting similar findings that insulin administration pre-operatively may be protective against the development of EuDKA." (PMID 40887509, 2025). "The apparent overlap between T1D and T2D that occurs in obese young patients has resulted in some controversy regarding mixed forms of diabetes, but this does raise unsettling questions about the treatment of T1D in the presence of an insulin-resistant phenotype." (PMID 40244115, 2025). "Diabetes mellitus (DM) is a condition characterized by a disruption in metabolism characterized by persistent hyperglycemia or hypoglycemia, accompanied by changes in carbohydrate, lipid, and protein metabolisms, leading to insulin deficiency or elevated insulin levels." (PMID 40264643, 2025). "This pathology was also associated with low and high levels of fasting insulin, as levels of insulin is often, but not always, associated with diabetes mellitus." (PMID 39859258, 2025). "Notably, all participants (100.0%) had received prior counseling in carbohydrate counting, indicating a uniformly high level of exposure to structured diabetes self-management tools before transitioning to insulin pump therapy." (PMID 41146752, 2025). "Notably, 19 patients shifted from insulin treatment to oral medications or lifestyle adjustments after receiving a specific genetic diagnosis for diabetes." (PMID 39504571, 2025). "Stratified analyses by age of diabetes onset and insulin use as proxy indicators for diabetes types consistently demonstrated negative associations between HRR and DR risk across subgroups." (PMID 40862119, 2025). "Targeting key molecules within the insulin signaling pathway may offer new opportunities for diabetes treatment." (PMID 39948335, 2025). "Age at diabetes diagnosis, weight loss, ΔGlucose (the change in glucose over the year preceding diabetes onset);laboratory values: HbA1C; alkaline phosphatase; hemoglobin; anemic prescribed anti-diabetic medicines (insulin, metformin, or oral anti-glycemic agents) and proton pump inhibitors." (PMID 41347135, 2025). "While the effects on glycemia and insulin sensitivity are generally positive, further research is needed to confirm the applicability and effectiveness of these breaks, especially in specific populations such as older adults and individuals with diabetes." (PMID 41356824, 2025). "Thus, elevated fasting insulin levels, higher HOMA-IR values, and increased C-peptide levels serve as important biomarkers in patients with diabetes that correlate with a higher risk of EC." (PMID 41440200, 2025). "Diabetes arises when the pancreas produces insufficient insulin or when insulin action is impaired." (PMID 41158567, 2025).
diabetes (continued). "In our life course cohort, which included individuals who were free of diabetes at baseline, adolescent participants showed the lowest level of insulin sensitivity but had the highest level of insulin secretion compared with their counterparts in childhood and adulthood." (PMID 39611962, 2025). "Notably, a 16-week VD3 intervention effectively ameliorated these metabolic disturbances, suggesting that VD3 supplementation enhance insulin sensitivity and potentially delay diabetes onset in prediabetic individuals." (PMID 40746531, 2025). "Furthermore, the technologies used to deliver insulin and measure glucose have improved; for example, in the UK, hybrid closed loop systems are now the standard of care for people with type 1 diabetes mellitus." (PMID 40480914, 2025). "Diabetes, a chronic and serious condition resulting from the lack of production or inefficient use of insulin, is a major cause of morbidity and mortality and one of the fastest growing global health emergencies of the 21st century." (PMID 40732974, 2025). "Furthermore, hyperglycemia induces protein kinase C signaling, leading to aldosterone activation and increased MR expression, while MR activation impairs insulin sensitivity, leading to diabetes progression." (PMID 40955522, 2025). "Non-statin users also had lower body mass indexes and waist circumferences and a lower proportion of cardiovascular comorbidities, including hypertension, chronic kidney disease, cardiovascular disease, prolonged diabetes mellitus, and the use of insulin or multiple oral hypoglycemic agents." (PMID 40421191, 2025). "Diabetes classification, disease duration, and insulin usage duration." (PMID 41585798, 2025). "Insulin and insulin‐sensitizing medications demonstrate antithrombotic properties that may confer stroke protection in diabetes." (PMID 41383356, 2025). "Thus, OP represents a promising non-invasive transdermal insulin delivery system, offering an ideal alternative to hypodermic injections for diabetes management." (PMID 41261125, 2025). "However, having frequent in-person clinic visits to review SMBG and adjust insulin doses is impractical, given the massive patient load and long waiting time of many diabetes clinics." (PMID 39924297, 2025). "However, the relative importance of reduced fat mass vs improvement of diabetes and insulin sensitivity for these changes needs to be addressed in future studies." (PMID 39943818, 2025). "Insulin treatment remains the mainstay of treatment in most women with established diabetes." (PMID 40125239, 2025). "Additionally, Rh4 has demonstrated a significant effect in alleviating diabetes symptoms, normalizing glucose metabolism, and enhancing insulin secretion, primarily through increased Nrf2 expression." (PMID 40432897, 2025). "It is important to know insulin complications when managing diabetes." (PMID 40226177, 2025). "Existing trials of conversational AI have demonstrated improvements in insulin adherence and glycemic control in patients with type 2 diabetes, medication adherence in patients with hypertension and diabetes, and symptoms of depression and anxiety in college students." (PMID 40829121, 2025). "Diabetes mellitus is defined by either inadequate secretion of insulin or resistance to insulin." (PMID 40438603, 2025). "Of all 13 investigated histological features, biomarkers related to diabetes and insulin resistance were predominantly indicative of fibrosis and ballooning (diabetes, HbA1c, glucose, insulin, HOMA-IR), of Mallory's hyaline (HbA1c, glucose) and, to a lower extent, of the NAS score (HbA1c)." (PMID 39702686, 2025). "The patient was educated on diabetes management, including insulin injections and SMBG." (PMID 41020242, 2025). "Insulin may be harmful due to the increased risk of fluidretention with its use; pooled analysis of RCT data indicates a significantlyhigher rate of all-cause mortality and HF hospitalizations in patients with HFand diabetes treated with insulin." (PMID 40475725, 2025).
diabetes (continued). "Type 2 diabetes mellitus (T2DM) is a metabolic disorder syndrome characterized by hyperglycemia resulting from defective insulin secretion, which can induce chronic damage and functional impairment in tissues such as blood vessels, kidneys, and the nervous system." (PMID 40565724, 2025). "Similarly, Turrin and Trujillo found that many patients undergoing insulin pump therapy faced challenges related to diabetes numeracy, particularly older individuals and those with higher A1c levels." (PMID 40566297, 2025). "The CRI evaluates six independent predictors of major cardiac complications: high-risk surgery, history of ischemic heart disease, history of heart failure, history of cerebrovascular disease, diabetes requiring insulin therapy, and preoperative serum creatinine > 2 mg/dL." (PMID 40964552, 2025). "Future research should be focused on deciphering the specific mechanisms by which BMP can affect insulin secretion or identity loss in β‐cells and whether modulation of BMP signaling might be beneficial in the context of diabetes." (PMID 39499224, 2025). "Where patients are unable to achieve glycemic control early in pregnancy and develop GDM or have existing diabetes before pregnancy, a targeted combination of lifestyle intervention and insulin treatment should be implemented to improve maternal and neonatal outcomes." (PMID 40137145, 2025). "Endocrine treatment consisted of multiple hormone replacement therapies: insulin for type 1 diabetes mellitus (despite marked glycemic variability and recurrent hypoglycemic episodes), oral prednisone for secondary adrenal insufficiency, and levothyroxine for secondary hypothyroidism." (PMID 40823579, 2025). "Besides antigen-specific Treg induction in the EAE model, we also observed an increase in insulin-specific Tregs in the spleens of animals receiving TPM-T1D before diabetes onset together with a reduction in T1D incidence." (PMID 40165970, 2025). "The phenomenon of attenuated uric acid lowering in patients with diabetes might be explained by antagonist effects of insulin in modulating urate transporters in the kidney, which has been demonstrated in animal studies." (PMID 39277784, 2025). "Previous studies suggest that metabolic factors such as diabetes and insulin treatment may influence the TyG index." (PMID 41021613, 2025). "Mg may contribute to the development and progression of diabetes by affecting insulin resistance, insulin secretion, inflammatory responses, and oxidative stress." (PMID 40103795, 2025). "This approach enables more accurate glucose management, which may reduce diabetes-related problems while also reducing the frequency of hypoglycaemia or hyperglycaemia episodes and overall insulin dose." (PMID 40574088, 2025). "Insulin resistance associated with circulating insulin and glucose levels in the entire sample irrespective of diabetes or malaria status." (PMID 40802820, 2025). "In support of the principles of circular economy and mitigation of product carbon, several pilot studies illustrate opportunities to utilize more sustainable product innovations in diabetes care, including reusable insulin delivery pens and recycling schemes for insulin delivery pens." (PMID 41332366, 2025). "Moreover, many anti-diabetic drugs other than insulin are contraindicated and require careful dose-adjustment in patients with liver cirrhosis, making the selection of a suitable drug for diabetes treatment in these patients challenging." (PMID 40704640, 2025). "However, obesity is closely linked with insulin resistance (IR), where an impaired cellular response to insulin results in hyperglycemia and serves as a precursor to type 2 diabetes mellitus (T2DM)." (PMID 40689212, 2025). "Hypoglycemia is a major complication of insulin therapy, particularly in type 1 diabetes mellitus." (PMID 41675061, 2025). "A lot of insulin and diabetes research is about this question." (PMID 39916408, 2025).
diabetes (continued). "Increasing circulating levels of Acrp30 may enhance insulin sensitivity and facilitate the management of blood glucose levels, positioning Acrp30 as a promising therapeutic target for diabetes mellitus treatment." (PMID 40141412, 2025). "This reduction in insulin secretion, combined with insulin resistance and increased glucose production, can result in significant corticosteroid-induced hyperglycemia in patients with diabetes." (PMID 40428894, 2025). "Adjusted for gender, age, smoking status, duration of diabetes, BMI, SBP and DBP, LDL-C, eGFR, Charlson's comorbidity index, and use of anti-hypertensive drugs, oral antidiabetic drugs, including metformin, sulphonylureas and other oral diabetes drugs, insulin, and lipid-lowering agents." (PMID 41282290, 2025). "By maintaining high-affinity binding and inducing prolonged activation of GLP-1R, dulaglutide effectively enhances insulin secretion, inhibits glucagon release, and delays gastric emptying—mechanisms critical for glycemic control in type 2 diabetes mellitus (T2DM)." (PMID 41226200, 2025). "Differential effects of various CTRPs and other adipokines on insulin signaling and lipid metabolism may contribute to paradoxical outcomes, potentially exacerbating conditions like obesity or diabetes in some contexts." (PMID 40852589, 2025). "Similarly, while AI-driven diabetes management provides predictive analytics for glucose trends and insulin adjustments, concerns about data privacy, algorithmic bias, and regulatory hurdles must be addressed before widespread clinical adoption." (PMID 40217595, 2025). "GRH may reflect the first phase of glucose dysmetabolism before overt diabetes, a suboptimal primary insulin response to glucose loads, but this remains speculative." (PMID 40859194, 2025). "Insulin is a key life-saving drug for patients with diabetes and is used clinically worldwide." (PMID 40191128, 2025). "The third stage marks early decompensation, where β-cells can no longer meet the body’s insulin demands, causing glucose levels to rise rapidly and leading to overt diabetes." (PMID 40162315, 2025). "Moreover, the DiaRem score ranges from 0 to 22 and incorporates HbA1c, insulin use, age, and other diabetes medications into the scoring system." (PMID 40005466, 2025). "Therefore, the core of the pathogenesis of diabetes and its complications lies in the insulin dysfunction." (PMID 41030912, 2025). "Moreover, these people tend to have trouble with insulin dosing and managing diabetes (U.S. Department of Health and Human Services, 2010, 2014)." (PMID 39902319, 2025). "Diabetes mellitus is a common chronic metabolic disease seen throughout the world, and it is defined by hyperglycemia that persistently occurs due to inadequate insulin secretion, insulin resistance, or both." (PMID 41444816, 2025). "Traditional treatments for diabetes include lifestyle modifications, oral hypoglycemic agents (such as metformin, α-glucosidase inhibitors, and insulin sensitizers), and injectable medications (such as insulin and glucagon-like peptide-1)." (PMID 40474972, 2025). "Diabetes mellitus in dogs occurs when the animal does not produce enough insulin, causing high blood glucose levels, which can damage organs." (PMID 40723467, 2025). "In addition to intensifying insulin therapy, control of diabetes needs facilities for self-monitoring of blood glucose and urine testing strips for ketones." (PMID 40904852, 2025). "Alpha-blockers specifically reduce nocturia episodes in men with diabetes with BPH while improving peripheral insulin sensitivity and attenuating orthostatic hypotension in diabetic autonomic neuropathy, potentially explaining the enhanced protective effect observed." (PMID 40283195, 2025). "Long-acting therapies, including insulin analogs, may be beneficial in establishing an optimal insulin control regimen for pregnant women with diabetes." (PMID 40137145, 2025).